KL (klotho)
Diseases named in the same sentence as KL in open-access papers (continued):
Sharing a sentence is not in itself a finding about the gene and the disease.
infection (11 papers, 2018 to 2025). The state of being infected such as from the introduction of a foreign agent such as serum, vaccine, antigenic substance or organism. "Klotho, a protein that is predominantly expressed in renal tubular cells, protects against acute and chronic kidney injury caused by various insults, including ischemia/reperfusion, chemical agents, infection, and obstruction." (PMID 35847036, 2022). "The number of IMs increased in the lungs of klotho KO mice at 1 day post-infection and subsequently deceased at 3 days post-infection." (PMID 33329595, 2020). "The number of alveolar macrophages in klotho KO mice was lower than that in klotho WT mice, except for 1 day post-infection." (PMID 33329595, 2020). "The expression level of CD11b on AM in the lungs of klotho WT mice was significantly increased at 1 day post-infection and subsequently gradually decreased (WT)." (PMID 33329595, 2020). "An increase in the rate of fibrosis in mouse kidney tissue was observed in the CKD + IS compared to CKD group, which was alleviated following infection with Ad-Klotho." (PMID 32464602, 2020). "To clarify the pathogenicity of A. baumannii in the elderly, we investigated immune responses to A. baumannii ATCC 19606 infection in klotho knockout (KO) mice, the mouse model of aging." (PMID 33329595, 2020). "The expression level of CD11b on neutrophils in the lungs of klotho WT mice was significantly increased after infection with A. baumannii (WT)." (PMID 33329595, 2020). "The level of IL-10 mRNA in the lungs of klotho KO mice increased at 1 day post-infection and subsequently decreased significantly." (PMID 33329595, 2020). "The serum level of IL-10 increased in klotho WT and KO mice after infection and was significantly higher in klotho KO mice than in klotho WT mice at 1 day post-infection." (PMID 33329595, 2020). "Flow cytometry revealed that the number of neutrophils in the blood before infection was lower in klotho KO mice than in klotho WT mice." (PMID 33329595, 2020). "The level of IL-10 mRNA in the lungs of klotho WT mice significantly increased at 1 day post-infection and decreased at 3 days post-infection." (PMID 33329595, 2020). "There was a significant difference between the expression level of Ly-6G on neutrophils in the lungs of klotho WT mice and KO mice at 3 days post-infection." (PMID 33329595, 2020). "The number of CD11blow conventional DC in the lungs of klotho KO mice hardly increased after the infection, whereas that of klotho WT mice increased at 3 days post-infection and subsequently decreased at 7 days post-infection." (PMID 33329595, 2020). "The number of monocytes in the blood of klotho KO mice significantly increased at 1 day post-infection and subsequently decreased at 3 days post-infection." (PMID 33329595, 2020). "CD11b expression on neutrophils and alveolar macrophages in the lungs of klotho KO mice was seldom upregulated by the infection." (PMID 33329595, 2020). "The level of CXCL1 mRNA in the lungs before infection was higher in klotho KO mice than in klotho WT mice." (PMID 33329595, 2020). "Presently, the induction level of IL-1β, CXCL1 (KC), CXCL2 (MIP-2), and CCL2 (MCP-1) mRNA in the lungs after infection was significantly higher in klotho KO mice than in klotho WT mice." (PMID 33329595, 2020). "In this study, lung bacterial burden remained in klotho KO mice at 7 days post-infection in spite of the infection established by the intravenous inoculation of A. baumannii." (PMID 33329595, 2020). "In contrast, the expression level of CD11b on neutrophils in the lungs of klotho KO mice was slightly increased at only 1 day post-infection (KO)." (PMID 33329595, 2020).
infection (continued). "The number of eosinophils significantly decreased in the blood of klotho WT and KO mice at 1 day-post infection and subsequently increased." (PMID 33329595, 2020). "Neutrophils, eosinophils, interstitial macrophages, and monocyte/dendritic cell subset in the lungs of klotho KO mice were transiently induced after infection with A. baumannii." (PMID 33329595, 2020). "We analyzed the levels of proinflammatory cytokines in the sera of klotho WT and KO mice before and after infection with A. baumannii." (PMID 33329595, 2020). "The collective results suggested that proinflammatory responses were strongly and transiently induced in the lungs of klotho KO mice after infection with A. baumannii." (PMID 33329595, 2020). "The level of TLR2 mRNA was significantly lower in the lungs of klotho KO mice than in those of klotho WT mice at 3 days post-infection." (PMID 33329595, 2020). "The number of AM in the lungs of klotho KO mice was slightly increased at 1 day post-infection and subsequently decreased to the pre-infection level at 3 days post-infection, whereas the cell number in klotho WT mice slightly decreased after infection." (PMID 33329595, 2020). "A clinical score (ruffled fur) was observed for one of 15 klotho KO mice at 1 day post-infection and one of six klotho KO mice (inactive unless prodded) at 6 days post-infection." (PMID 33329595, 2020). "The level of IL-6 mRNA in the lungs of klotho WT mice slightly increased at 1 day post-infection and subsequently deceased at 3 days post-infection." (PMID 33329595, 2020). "IL-1β, CXCL1, CXCL2, and CCL2 expression was significantly higher in the lungs of klotho KO mice infected with A. baumannii than in those of klotho WT mice at 1 day post-infection." (PMID 33329595, 2020). "The level of CXCL2 mRNA was significantly higher in the lungs of klotho KO mice than in those of klotho WT mice at 1 day post-infection." (PMID 33329595, 2020). "Although the number of neutrophils increased in the lungs of klotho KO mice after infection with A. baumannii, the expression level of CD11b on neutrophils was hardly upregulated." (PMID 33329595, 2020). "We analyzed the number of immune cells in the blood of klotho WT and KO mice after infection with A. baumannii." (PMID 33329595, 2020). "The level of IL-1β mRNA was significantly higher in the lungs of klotho KO mice than in those of klotho WT mice at 1 day post-infection." (PMID 33329595, 2020). "In contrast, the number of neutrophils in the blood of klotho KO mice increased at 3 days post-infection and subsequently decreased at 7 days post-infection." (PMID 33329595, 2020). "Of note, although the serum level of IL-6, CXCL1, and CCL7 in klotho WT mice decreased at 3 days post-infection, those in klotho KO mice was maintained until 3 days post-infection." (PMID 33329595, 2020). "The level of CCL7 mRNA increased in the lungs of klotho WT and KO mice at 1 day post-infection and subsequently decreased at 3 days post-infection." (PMID 33329595, 2020). "The level of IL-10 mRNA before infection was significantly higher in the lungs of klotho KO mice than in those of klotho WT mice." (PMID 33329595, 2020). "The number of neutrophils in the blood of klotho WT mice significantly decreased at 1 day-post infection and subsequently increased gradually." (PMID 33329595, 2020). "The expression level of CD11b on AM in the lungs of klotho KO mice before infection was significantly higher than that of klotho WT mice before infection and slightly increased at 1 day post-infection (KO)." (PMID 33329595, 2020). "The level of CCL2 mRNA in the lungs at 1 day post-infection was significantly higher in klotho KO mice than in klotho WT mice." (PMID 33329595, 2020). "Flow cytometry revealed that the number of neutrophils in the lungs of klotho KO mice gradually increased until 3 days post-infection and decreased at 7 days post-infection, whereas that of klotho WT mice significantly increased at 1 day post-infection." (PMID 33329595, 2020).
infection (continued). "The level of CXCL2 mRNA in the lungs of klotho KO mice increased at 1 day post-infection and subsequently decreased at 3 days post-infection." (PMID 33329595, 2020). "The expression level of Ly-6G on neutrophils in the lungs of klotho WT mice gradually increased after the infection, whereas that of klotho KO mice hardly increased after infection with A. baumannii." (PMID 33329595, 2020). "The body weight of klotho KO mice increased at 1 day post-infection and subsequently decreased gradually until 7 days post-infection." (PMID 33329595, 2020). "In the current study, we established an aged mouse model of A. baumannii infection using klotho KO mice and evaluated the immune responses in the mice before and after infection." (PMID 33329595, 2020). "The level of TNF-α mRNA in the lungs of klotho WT mice gradually increased after infection, whereas those of klotho KO mice significantly increased at 1 day post-infection and subsequently decreased at 3 days post-infection." (PMID 33329595, 2020). "Another study found that overexpression of secreted Klotho in response to infection of neurons by intraventricular injection with a lentivirus-based expression system significantly improved the performance of SAMP8 mice in the Y-maze task." (PMID 31001090, 2019). "A phylogenetic comparison of KL sequences demonstrated a substantial level of KL diversity within S. marcescens as a species and a strong delineation between KL sequences originating from infection isolates versus environmental isolates." (PMID 35353877, 2022). "To test whether the restoration of KL expression could rescue podocyte cytoskeleton disruption induced by HG, we overexpressed KL in HG-cultured podocytes via Ad-KL infection." (PMID 35480629, 2022). "The notion that environmental and clinical isolates of S. marcescens differ both genetically and phenotypically, together with our observations of CPS involvement in infection, prompted us to determine if there is a relationship between KL type and isolation source." (PMID 35353877, 2022). "Additionally, the level of CXCL1 mRNA in the lungs at 1 day post-infection was significantly higher in klotho KO mice than in klotho WT mice." (PMID 33329595, 2020). "Moreover, there was a significant difference between the expression level of CD11b on neutrophils in the lungs of klotho KO mice and WT mice at 3 days post-infection." (PMID 33329595, 2020). "Since neutrophils and macrophages play an important role in the clearance of A. baumannii, we analyzed the number of immune cells in the lungs of klotho WT and KO mice after infection with A. baumannii, based on the classification of the lung innate immune cell population." (PMID 33329595, 2020). "Additionally, there were fewer AM in klotho KO mice than in klotho WT mice, except for 1 day post-infection." (PMID 33329595, 2020). "The level of CXCL1 mRNA in the lungs of klotho WT mice gradually increased after infection." (PMID 33329595, 2020). "Although the present study suggests the disruption in the function and/or differentiation of immune cells in klotho KO mice, it remains unclear how klotho KO mice died from infection with A. baumannii." (PMID 33329595, 2020). "However, the number of monocytes in the blood before and after infection was lower in klotho KO mice than in klotho WT mice." (PMID 33329595, 2020). "The level of CCL2 mRNA in the lungs of klotho WT mice gradually increased after infection, whereas those of klotho KO mice significantly increased at 1 day post-infection and subsequently decreased at 3 days post-infection." (PMID 33329595, 2020). "Additionally, the production of proinflammatory cytokines in the sera after infection with A. baumannii were prolonged in klotho KO mice compared with klotho WT mice." (PMID 33329595, 2020). "Therefore, we evaluated body weight, clinical score, and survival rate of klotho WT and KO mice after infection via intravenous inoculation of A. baumannii ATCC 19606." (PMID 33329595, 2020).
infection (continued). "In addition, the expression level of Ly-6G as a maturation marker of neutrophils was analyzed in klotho WT and KO mice after infection with A. baumannii." (PMID 33329595, 2020). "The expression levels of CCL7 mRNA were comparable between klotho WT and KO mice after infection." (PMID 33329595, 2020). "However, the expression level in the lungs of klotho KO mice was upregulated at 1 day post infection of A. baumannii." (PMID 33329595, 2020). "However, the level of TLR9 mRNA in the lungs of klotho KO mice was significantly decreased compared with that of klotho WT mice at 3 days post-infection." (PMID 33329595, 2020). "The number of macrophages in the blood of klotho KO mice significantly increased at 1 day post-infection and subsequently decreased gradually, whereas those of klotho WT mice increased at 3 day post-infection and subsequently decreased at 7 days post-infection." (PMID 33329595, 2020). "Additionally, the number of AM in klotho KO mice was lower than that in klotho WT mice, except for 1 day post-infection." (PMID 33329595, 2020). "Additionally, the level of TNF-α mRNA in the lungs at 3 days post-infection was significantly lower in klotho KO mice than in klotho WT mice." (PMID 33329595, 2020). "However, although klotho WT mice showed decreased weight after infection with A. baumannii, klotho KO mice showed only a slight weight change after the infection." (PMID 33329595, 2020). "Additionally, although klotho WT mice did not die of A. baumannii infection, klotho KO mice were more susceptible, as evidence by the 56% survival rate at 7 days post-infection." (PMID 33329595, 2020). "Therefore, we evaluated the expression level of CD11b on neutrophils to determine whether neutrophils were activated in the lungs of klotho KO mice after infection with A. baumannii." (PMID 33329595, 2020). "In our previous KL comparison, the KL1 and KL2 lineages had the greatest number of representatives in our genome cohort, and both were overwhelmingly composed of infection isolates." (PMID 40237485, 2025). "These research findings should attract more attention towards the possible interplay between the pathogenesis from infection by SARS-CoV-2 (as well as other coronaviruses, potentially) and the anti-aging protein Klotho." (PMID 38133288, 2023). "Following infection, the levels of TLR9 mRNA in the lungs of klotho WT and KO mice increased at 1 day post-infection and subsequently decreased at 3 days post-infection." (PMID 33329595, 2020). "Since TLRs play an important role in eliciting proinflammatory cytokines during infection with A. baumannii, we analyzed the expression levels of TLR2, 4, and 9 in the lungs of klotho WT and KO mice after infection with A. baumannii." (PMID 33329595, 2020). "The overexpression systems combined localized stereotaxic infection of CA1 neurons in the dorsal-intermediate hippocampus and CaMKII::Cre-floxed expression that allowed highly targeted Klotho overexpression." (PMID 31001090, 2019). "Although neutrophils were induced in klotho KO mice after infection with A. baumannii, the burden of the lung bacteria was not completely eliminated in the mice at 7 days post-infection." (PMID 33329595, 2020). "TNF-α, IL-6, CXCL1, CCL2, and CCL7 levels significantly increased in the sera of klotho WT and KO mice at 1 day post-infection, while the level of IL-12 was not." (PMID 33329595, 2020). "The level of IL-6 mRNA in klotho KO mice was not increased at 1 day post-infection and was decreased at 3 days post-infection." (PMID 33329595, 2020). "Bacteria were detected in the lungs of klotho KO mice but not klotho wildtype (WT) mice at 7 days post-infection." (PMID 33329595, 2020). "In contrast, bacteria were detected in the lungs of three of four klotho KO mice at 7 days post-infection (KO), but not in the spleen and blood (KO)." (PMID 33329595, 2020).
infection (continued). "In contrast, the levels of TLR4 mRNA were comparable between klotho WT and KO mice, and were not altered in their lungs after the infection." (PMID 33329595, 2020). "The number of eosinophils in the lungs of klotho KO mice significantly increased at 1 day post-infection and subsequently decreased until 7 days post-infection, whereas klotho WT mice showed no induction of eosinophils after infection." (PMID 33329595, 2020). "The serum level of IFN-γ significantly increased in klotho WT mice at 1 day post-infection, whereas that did not increase in infected klotho KO mice." (PMID 33329595, 2020). "To determine if Klotho overexpression affects synaptic transmission, we tested CA1 hippocampal synaptic plasticity using acute hippocampal slices from Vehicle and Klotho group mice 2 months after infection with the virus." (PMID 31001090, 2019). "Although we analyzed ROS production in monocytes as well as neutrophils in klotho KO mice infected with A. baumannii, it was not clear whether those cells induced ROS in response to the infection." (PMID 33329595, 2020).
kidney (11 papers, 2014 to 2026). "We report that Rhein is an impressive up-regulator of Klotho and it markedly reversed Klotho down-regulation in unilateral ureteral occlusion-induced fibrotic kidney." (PMID 27703201, 2016). "We found that increased expression of genes in both AKI and CKD models, is primarily transcriptionally mediated while post-transcriptional processes may play a more significant role in gene downregulation in the setting of kidney injury (e.g. Klotho)." (PMID 30552397, 2018). "GDF-15 preserved Klotho expression during acute kidney injury and fibrosis, indicating a relationship between GDF-15 and Klotho expression." (PMID 40362229, 2025).
neurological disorders (9 papers, 2021 to 2025). "Notably, the microglia and macrophage gene data indicate significant differences between KLOTHO-deficient and WT treatment conditions related to immune function, which is strongly tied to neurological disease." (PMID 40869172, 2025). "An increasing amount of evidence suggests that klotho exerts a neuroprotective effect in the central nervous system and plays a significant role in neurological disorders." (PMID 40452763, 2025). "This review also highlights some limitations of the research on Klotho in nervous system diseases." (PMID 37894946, 2023). "Moreover, the study did not control for all chronic diseases that may affect serum KL levels, such as respiratory, circulatory, urinary, and nervous system disorders." (PMID 41465998, 2025).